RDUR (RIG-I dependent antiviral response regulator RNA)
Description:
Could play a role in innate immunity against viruses.
Synonyms: LINC02085
Gene: Long non-coding RNA gene on chromosome 3 (101,868,657 to 101,997,926, forward strand). Ensembl gene ENSG00000214407.
Diseases named in the same sentence as RDUR in open-access papers:
RDUR is named in the same sentence as 2 diseases in open-access papers, as found by Europe PMC text mining. Sharing a sentence is not in itself a finding about the gene and the disease. The quoted sentences say what the papers report.
viral infection (4 papers, 2021 to 2023). "Together, the results demonstrate that RDUR is an important lncRNA acting as a critical regulator of innate immunity against the viral infection." (PMID 34054851, 2021). "Together, these results indicate that RDUR is an important host factor that functions as positive regulator of innate immunity against virus infection." (PMID 34054851, 2021). "On the other hand, we found that while NF-κB positively regulated the expression of RDUR, increased expression of RDUR, in turn, inactivated NF-κB through a negative feedback mechanism to suppress excessive inflammatory response to viral infection." (PMID 34054851, 2021). "It is concluded that RDUR is a critical regulator of innate immunity against viral infection." (PMID 35836133, 2022). "One of mechanisms underlying RDUR function is likely through formation of a complex with ILF2/ILF3 that might regulate the translation of IFN-β1 and some ISGs during the viral infection." (PMID 34054851, 2021). "For example, lnc-ISG20 and ISR function as interferon-stimulated genes (ISGs), and LncRNA-155, NEAT1, SAAL, RDUR, AVAN and IVRPIE can suppress IAV replication by promoting innate immune responses to viral infection." (PMID 37308824, 2023). "Hence, RDUR-related cellular response might be a universal defense against virus infection." (PMID 34054851, 2021).
infection (1 paper, 2021). The state of being infected such as from the introduction of a foreign agent such as serum, vaccine, antigenic substance or organism. "RDUR is expressed in various human and mouse cells and greatly upregulated by infection with different strains of IAV and other viruses, including SeV, MDRV, HSV and PRV." (PMID 34054851, 2021).